CTNNB1 (catenin beta 1)
Diseases named in the same sentence as CTNNB1 in open-access papers (continued):
Sharing a sentence is not in itself a finding about the gene and the disease.
tumor (continued). "We presented CTNNB1 (Catenin β-1), a key downstream component of the canonical Wnt signaling pathway; it was also found relevant to explain results from the transcriptomic analysis and to discuss the tumor immune-microenvironment regulation." (PMID 34944876, 2021). "In conclusion, analysis of ctDNA revealed tumor mutations that were not apparent in single tumor biopsies, and the combined analysis of ctDNA and tumor tissue increased the detection rate of CTNNB1 mutation in HCC patients." (PMID 33827453, 2021). "Sanger sequence of gDNA from the tumor nodules showed precise conversion of S45F in Ctnnb1." (PMID 33837189, 2021). "Because both tumor and non-tumor sections showed similar membranous β-catenin staining, it was not suggested that the large deletion of CTNNB1 gene caused the loss of β-catenin antigenicity." (PMID 33580445, 2021). "Morphological parameters such as the absence of mucinous differentiation and the absence of MELF pattern showed high sensitivity to identify CTNNB1-mutated tumours." (PMID 34420090, 2021). "The results demonstrated that DF cases harbouring CTNNB1 mutations were derived from larger-sized tumours (7.655 ± 0.642 cm) compared with DF cases without CTNNB1 mutation (4.973 ± 0.952 cm; p = 0.020)." (PMID 33914771, 2021). "Based on a large proportion of samples being CTNNB1 mutation negative in both plasma and tumor tissue, the agreement between plasma and tissue mutational status was 91.7% (kappa value 0.53 (0.20–0.85), P = 0.0007)." (PMID 33827453, 2021). "Basically, higher miR-499a-5p expression represents an advantage for the tumor cells which may activate transcription of pro-tumorigenic genes besides normal CTNNB1." (PMID 34804952, 2021). "Next, we investigated the role of CTNNB1 in NSCLC cell tumor formation in an animal model." (PMID 34465343, 2021). "The occurrence of a germline CTNNB1 variant has only been reported as an inactivating mutation, constituting another distinct phenotype without tumor manifestations, in two siblings, of whom the parents most likely harbored germline mosaicism." (PMID 31598872, 2020). "A homozygous CTNNB1 mutation is not normally observed in tumor cells as the mutant allele functions as a dominant oncogene." (PMID 33379206, 2020). "Furthermore, qRT-PCR results showed that circXPO1 expression level was positively correlated with CTNNB1 in LUAD tumor tissues (r = 0.69, P < 0.01)." (PMID 33268793, 2020). "Aberrant expression of E-cadherin, however, was neither exclusive to CTNNB1-mutated tumours nor did all CTNNB1 mutated CRCs display reduced E-cadherin expression." (PMID 33115416, 2020). "In present study, we found that overexpression of CTNNB1 could abrogate the tumor-inhibiting ability of sh-FLVCR1-AS1." (PMID 32518523, 2020). "In agreement with this is the fact that the WT1 mutant Wilms8 tumor and cell culture has no additional pathogenic mutation except for CTNNB1." (PMID 33379206, 2020). "Interestingly, we observed high mRNA expression of the signaling molecules AKT, PTEN, STATs, and CTNNB1 coding for beta-catenin in tumor and immune cell regions of both NET G3 and NEC." (PMID 33228231, 2020).
tumor (continued). "This type of HCC is characterized by the lack of CTNNB1 mutations, global hypermethylation, expression of PD-1 and PD-L1 in tumor infiltrating lymphocytes (TILs), and expression of PD-L1 in tumors." (PMID 32443599, 2020). "In a thorough study of the tumorigenic capacity of 14 different mutant forms of CTNNB1 with Yap-1, Zhang and colleagues showed that specific mutant forms of CTNNB1 determine HB tumor growth rates, survival, histologic features, metabolic features, and transcriptional profiles." (PMID 31979130, 2020). "The tumor-promoting mutations in CTNNB1 (β-catenin), APC, or AXIN genes are also absent in this cell line." (PMID 32601309, 2020). "This analysis revealed that 1360 genes were differentially expressed between tumours with CTNNB1-mutations and tumours without CTNNB1-mutations." (PMID 31000732, 2019). "Finally, to determine if activation of the β-catenin pathway contributed to the tumor-promoting effects of miR-590-3p, SKOV3.ip1 cells were transiently transfected with a siRNA-targeting CTNNB1, the gene encoding β-catenin." (PMID 31013711, 2019). "Furthermore, the tumor volume curve almost remained uniform throughout the experimental procedure, which indicates the essential role of CTNNB1 siRNA knockdown in this cancer model." (PMID 31269666, 2019). "Our results suggest a role for Wnt signaling biology in this tumor, as we found elevated proteins associated with Wnt biology, enrichment of APC mutations, and the presence of an oncogenic mutation in CTNNB1." (PMID 31395880, 2019). "Due to mutation status changes of the WNT genes (APC and CTNNB1), NEFH might lose its tumor suppressor role, leading to apoptosis dysregulation." (PMID 31740709, 2019). "These tumors are typically treated with surgery; however, residual tumor and recurrence can pose a treatment quandary because little is known about the genetic landscape of these tumors beyond two defining mutations: BRAF V600E and CTNNB1." (PMID 31712784, 2019). "Using a next-generation sequencing assay, we documented genomic alterations in KRAS and CTNNB1, low tumor mutation burden (TMB), and an absence of microsatellite instability." (PMID 31266530, 2019). "We first confirmed CTNNB1 up regulation in HB tumor tissues." (PMID 31870368, 2019). "Investigation of the expression of genes involved in proliferation and apoptosis revealed subtle differences between tumours with and without CTNNB1 mutations." (PMID 31000732, 2019). "In our case, next-generation sequencing technology detected KRAS G12C and CTNNB1 G34R mutations, absence of microsatellite instability and low tumor mutation burden (three mutations per megabase)." (PMID 31266530, 2019). "Beta-catenin (β-catenin) is a protein encoded by CTNNB1 gene on band p12 placed on the short arm of chromosome 3, a region that is affected by a somatic alteration in the tumor." (PMID 30854333, 2019). "Although ACP cellular models have been used, these have not been molecularly characterised and in our hands, the CTNNB1 mutations that characterise the ACP tumours are lost in the culture cells." (PMID 30645190, 2019). "Significantly lower overall survival rate in patients with tumours harbouring alterations in APC/CTNNB1/ZNRF3 in comparison to those without mutation was observed." (PMID 29872083, 2018). "For example, intestinal epithelial cells are dependent on exogenous Wnt in culture but constitutively active Wnt signaling, due to genomic aberrations in genes such as APC and/or CTNNB1, often confers tumor cells with the ability to survive culture in Wnt‐free culture media." (PMID 29569246, 2018). "Expression levels of ZNRF3 mRNA were significantly higher in tumours harbouring the ∆(2 + 3) deletion (p = 0.0032) and missense mutations (p = 0.0210) in comparison to those without CTNNB1 mutations." (PMID 29872083, 2018).
tumor (continued). "In addition, AKT has been reported to regulate CTNNB1 phosphorylation and degradation in tumor invasion and development." (PMID 30112810, 2018). "Moreover, significant activation of WNT/CTNNB1 pathway has been shown to drive human Schwann cell transformation and tumor maintenance in development of MPNST." (PMID 30112810, 2018). "Analysis of Cyclin D1 protein expression showed significantly higher expression (p = 0.0095) in the samples with the deletion in comparison to analyzed tumours without CTNNB1 mutation." (PMID 29872083, 2018). "Activating β-catenin (Ctnnb1) mutations have previously been implicated in progression to carcinoma, but in a two-stage model where DEN is given as the initiator followed by treatment with phenobarbital as a tumour promoter." (PMID 29958939, 2018). "CTNNB1 mutations have been observed in approximately 10–15% of ACCs17–20, although aberrant activation of Wnt/β-Catenin signaling is observed in a much higher proportion of ACC tumours, most of them are not caused by known CTNNB1 mutations." (PMID 29872083, 2018). "Additionally, expression of CTNNB1 was increased in tumor samples in our data, suggesting that several elements of Wnt-signaling were dysregulated and that the stabilization of β-catenin needed to control cell growth was destroyed." (PMID 29464056, 2018). "Gain-of-function mutations in the CTNNB1 gene, as well as loss-of-function mutations in the APC and AXIN2 genes, activate the canonical Wnt/β -catenin signaling cascade that regulates self-renewal, survival, proliferation and differentiation of tumor cells." (PMID 29312609, 2017). "The cluster 1 was associated with a prevalent Asian ethnicity, high tumor grade, low differentiation score, low frequency of CDKN2A silencing, TERT promoter mutation and CTNNB1 mutation, high miR-181a expression and overexpression of proliferation marker genes." (PMID 28930164, 2017). "In case 1, tumour block 1a harboured a c.94G>GT mutation with a variant allele frequency (25%), whereas no CTNNB1 mutation was detected in block 1b and 1c." (PMID 28424422, 2017). "Moreover, we show that genetic and chemical downregulation of HGFL-RON signaling disrupts BCSC phenotypes and tumor growth by suppressing the RON-mediated phosphorylation/activation of β-CATENIN/CTNNB1 and its effector NF-κB/RELA." (PMID 28938607, 2017). "In particular, tumor cells surrounding ghost cells tended to be enriched in nuclear CTNNB1." (PMID 28658279, 2017). "In case 2, a c.110C>CG mutation in CTNNB1 was detected at high allelic frequency (80-100%) in tumour block 2a and 2b, but not in block 2c." (PMID 28424422, 2017). "By real-time qPCR, we further examined the expression of selected genes (Pkm, Ppp1r13l, Vamp3, Ctnnb1, Tbc1d4, Ppp1r21, C1qtnf9, Fgf3 and Efemp2) that are known to be involved in the tumor development or potentially relevant for establishment of malignant transformation." (PMID 29073177, 2017). "Within the KIRC tumour tissue data, the risk-associated allele of the surrogate SNP rs9821249 (r2=0.97 with rs67311347 in CEU) was weakly associated with higher expression of CTNNB1 (P=0.03)." (PMID 28598434, 2017). "The analyses of TERT promoter and CTNNB1 mutations on HCC tumor samples have not been performed in the Korean population, where HBV-related HCC is prevalent." (PMID 27661004, 2016).
tumor (continued). "Western blot in one tumor with CTNNB1 mutation (p.Ser45Pro) and four without CTNNB1 mutation, validated antibody specificity for β-catenin." (PMID 26815163, 2016). "Therefore, liganded TRβ acts as a tumor suppressor via inhibition of the expression of a potent tumor promoter, the CTNNB1 gene." (PMID 27814736, 2016). "For instance, the tumor growth of NPC was markedly attenuated when the expression of CTNNB1 was suppressed, which indicated that β-catenin may play an important oncogenic role in the migration and proliferation of NPC cells." (PMID 27769064, 2016). "One tumor (case 2) showed positive nuclei for beta-catenin (10%), without a CTNNB1 mutation after direct sequencing, and chromosome 6 monosomy." (PMID 26857864, 2016). "Furthermore as the tumor and the cell line have the same WT1 alteration but different CTNNB1 mutations this supports the model that the WT1 alteration occurs first, with a high selection pressure to acquire mutations in CTNNB1." (PMID 27213811, 2016). "CDH1 and CTNNB1 were expressed in 52.3 % (45/86) and 36.0 % (31/86) of tumor samples, respectively." (PMID 27600761, 2016). "Genetic markers in tumor tissue have been analyzed, in particular the CTNNB1-gene." (PMID 27565718, 2016). "The targets of β-catenin and the mechanism driving tumor progression in those patients carrying with β-catenin nuclear translocation in the absence of CTNNB1 mutation are issues of great importance to be addressed." (PMID 27100093, 2016). "Furthermore, in silico analysis demonstrated that miR-23b, miR-24-2, miR-141, and miR-449 act as tumour suppressors by inhibiting translation of CTNNB1 mRNA, while miR-150 was proposed to be acting as an oncomiR by modulating adenomatous polyposis coli (APC)." (PMID 26064134, 2015). "In mammary gland tumorigenesis, tumorigenesis was enhanced in Apc1638NCtnnb1+/- mice relative to Apc1638NCtnnb1+/+ mice, perhaps because Ctnnb1 functions as a tumor suppressor gene in Apc1638N mammary gland tumors via β-catenin’s role in E-cadherin-dependent tumor suppression." (PMID 26528816, 2015). "Two tumours with MLLT1 mutations also had CTNNB1 mutations; no MLLT1-mutant tumours had accompanying WT1, WTX, DROSHA, DGCR8, SIX1, or SIX2 mutations." (PMID 26635203, 2015). "Adenomatous polyposis coli (Apc) is a tumor suppressor that inhibits Wnt/Ctnnb1." (PMID 26092405, 2015). "It has also recently been suggested that ACP may be paracrine in nature (i.e. the CTNNB1 mutant cells may promote the proliferation of another cell type that actually populates the tumor)." (PMID 25990246, 2015). "Thus, AHR has a natural function as a tumor suppressor that is capable of downregulating CTNNB1 expression." (PMID 25286307, 2014). "Notably, LEF1 was identified as a regulator of FN1 and CDH1 expression in tumor-derived cells and was proposed to act in both, a CTNNB1-dependent as well as -independent manner." (PMID 23677615, 2013). "The majority of WT is wild type for WT1 and CTNNB1 and are found with perilobar nephrogenic rests; the initiating mutation in these tumours is not clear." (PMID 23239670, 2013). "Moreover, the expression of CTNNB1 and CDH1 were significantly associated with early tumor recurrence." (PMID 22962603, 2012). "Although not significant, this data suggests that tumour subtype was not the cause of better prognosis for the CTNNB1 nuclear tumours." (PMID 19293793, 2009). "Four other primary and one recurrent tumour that displayed CTNNB1 nuclear staining were sequenced and none contained mutations." (PMID 19293793, 2009). "This included three out of five tumours with high nuclear CTNNB1 expression." (PMID 19293793, 2009).
tumor (continued). "All high CTNNB1 nuclear tumours displayed less than 30% of nuclei positive." (PMID 19293793, 2009). "This included four primary and one recurrent tumour with CTNNB1 nuclear staining." (PMID 19293793, 2009). "Because of the very low frequency of tumours harbouring a CTNNB1 mutation, these mutations were not included in further analyses." (PMID 16356174, 2005). "Although eventual loss of Ctnnb1-mutant transformants was observed in mice rescued at 30 days after ENU treatment, mice rescued at 10 days had an increased tumour burden compared with that observed with initial Fbxw7 priming (mean 62 versus 53 tumours per mouse)." (PMID 41339549, 2026). "In addition, β-catenin (gene name: CTNNB1) is an important tumor promoter in BLCA." (PMID 40837414, 2025). "Thus, LOH at the region surrounding CTNNB1 may have resulted in a deleterious effect on tumor suppressor expression." (PMID 41279090, 2025). "However, there is a lack of understanding of the proteomic implications of CTNNB1 mutations in this type of tumor." (PMID 41227323, 2025). "Similarly, assessment of CTNNB1 exon 3 mutations in paired samples showed that 4 of 24 patients (16.7%) harboured mutations only in tumour tissue, with no cases presenting mutations restricted to non-tumour tissue (p = 0.1092)." (PMID 40650279, 2025). "In contrast, CTNNB1-mutant tumours, characterised by an immune-excluded microenvironment and resistance to PD-1 blockade, may benefit from therapies targeting the Wnt/β-catenin pathway, such as the small-molecule inhibitor PRI-724, currently under investigation." (PMID 40650279, 2025). "However, tumor size, rather than CTNNB1 mutation profile, was the main factor associated with event-free survival (EFS), as shown by their multivariate analysis." (PMID 39092348, 2024). "Six patients underwent molecular testing on tumor DNA: two carried marked IC2-LoM, two exhibited loss of heterozygosity (LOH) at chromosome 11p15, one carried somatic pathogenic variants of CTNNB1 and GNAS genes, and one carried somatic pathogenic variants of the MKRN3 and CYP17A1 genes." (PMID 39682154, 2024). "Five patients underwent molecular testing on tumor DNA: one exhibited a complex abnormal karyotype, one carried marked IC2-LoM, one showed a high level of genome-wide UPDpat, one exhibited LOH of chromosome 17p13, and one carried a somatic pathogenic variant in the CTNNB1 gene." (PMID 39682154, 2024). "Similarly, the CTNNB1 mutation found in HCC tumour cells but not in adjacent non-tumour cells has been demonstrated to activate the Wnt pathway." (PMID 39066215, 2024). "Additionally, GNAQ, GNAS, JAK2, NRAS, IDH2, and CTNNB1 are cancer-related genes that may be related to tumor metastasis." (PMID 36780540, 2023). "Notably, low-risk group patients had more CTNNB1 synapses, indicating non-inflammatory T-cell tumor tissues resistant to immunotherapy." (PMID 37081465, 2023). "Furthermore, Ctnnb1 expression was increased in tumours compared to both FL and RD livers and among the components of the β-catenin destruction complex, Axin1 and the known β-catenin target Axin2 was significantly upregulated, while Apc, Gsk3a and Gsk3b were not differentially expressed." (PMID 37907668, 2023). "Increasing evidence suggests that numerous m6A targets contribute to tumorigenesis, including Snail, CTNNB1, NANOG, APC, and genes associated with the Akt/mTOR pathway However, conflicting reports have indicated that METTL3 may function as a tumor suppressor in certain tumor types." (PMID 38012755, 2023). "Some cells may be non-neoplastic stromal cells infiltrating the tumor mass, which makes Sanger sequencing not suitable to detect CTNNB1 mutations in a subset of cases." (PMID 37377751, 2023). "However, in these mosaic non-tumor liver tissues, we neither identify CTNNB1 oncogenic mutation nor an alteration in other cancer driver genes." (PMID 37932266, 2023).